NLRP3 (NLR family pyrin domain containing 3)
Diseases named in the same sentence as NLRP3 in open-access papers (continued):
Sharing a sentence is not in itself a finding about the gene and the disease.
atherosclerosis (continued). "In the pathophysiology of atherosclerosis, NLRP3 inflammasome seems to play a pivotal role since it has been shown that cholesterol crystals and oxidized low-density lipoproteins (oxLDLs) are actively involved in NLRP3 activation." (PMID 36768804, 2023). "Clinical research on the signaling pathways leading to atherosclerosis has suggested that components of NETosis evoke NLRP3 inflammasome activation, which releases the proinflammatory cytokines IL-1β and IL-18." (PMID 36851139, 2023). "To date, anti-inflammatory therapy in atherosclerosis has targeted the NLRP3 inflammasome and upstream links of the IL-1β/IL-6/CRP axis." (PMID 36768404, 2023). "Along these lines, cholesterol crystals are recognized as NLRP3 inflammasome inducers in macrophages in atherosclerosis." (PMID 36744258, 2023). "Human atherosclerotic lesions exhibit elevated expression of key components of NLRP3 and inhibiting the NLRP3 inflammasome has been shown to notably reduce the progression of atherosclerosis." (PMID 37958528, 2023). "Nevertheless, the precise pathway through which the NLRP3 inflammasome impacts atherosclerosis is elusive; hence, comprehending the inflammasome activation pathways is pivotal for developing innovative targeted and efficient treatments." (PMID 37175869, 2023). "In this study, we aimed to examine the potential of highland barley in mitigating atherosclerosis by investigating its effects on the NLRP3 inflammasome pathway and gut microbiota." (PMID 37836470, 2023). "Recently, specific small-molecule inhibitors of NLRP3 have been developed to treat a variety of inflammasome-driven diseases like atherosclerosis." (PMID 37446157, 2023). "In the heart, activation of the NLRP3 inflammasome was related to the enhanced release of interleukin-1β (IL-1β) and the subsequent induction of atherosclerosis and heart failure." (PMID 37242177, 2023). "The NLRP3 inflammasome is triggered by different danger signals such as cholesterol crystals in atherosclerosis, uric acid crystals in gout and amyloid-beta in Alzheimer’s." (PMID 36851139, 2023). "Recent studies indicate that the TLR4/MyD88/NLRP3 pyroptosis signaling pathway plays a key role in the occurrence and development of cancer, heart failure, and atherosclerosis." (PMID 36733418, 2023). "Further exploration of its regulatory mechanism can provide further insight for potential treatment strategies targeting NLRP3 inflammasome to inhibit the development of atherosclerosis." (PMID 36910525, 2023). "Melatonin has proven to be effective in treating atherosclerosis by inhibiting NLRP3 inflammasome signaling pathway." (PMID 36911736, 2023). "Overactivation of the NLRP3 inflammasome can lead to the onset and progression of a variety of diseases, including diabetes mellitus, atherosclerosis, rheumatoid arthritis, ischemic heart disease, liver disease, kidney disease and so on." (PMID 37624173, 2023). "Nevertheless, most studies provide clear evidence identifying the NLRP3 inflammasome and IL-1β as major drivers of atherosclerosis development and progression." (PMID 37239938, 2023). "Recently, the NLR Family Pyrin Domain Containing 3 (NLRP3) inflammasome has gained attention as a major contributor to several important cardiometabolic diseases including atherosclerosis." (PMID 37284455, 2023). "Recent studies have shown that FGF21 can also act as a predictor of atherosclerosis by inhibiting mitochondrial fragmentation to reduce ROS production, and ultimately reducing NLRP3-mediated cellular death in endothelial cells to resist atherosclerosis." (PMID 37822930, 2023). "NLRP3 inflammasome plays a pivotal role in the progression of atherosclerosis, coronary artery disease (CAD), and myocardial ischemia–reperfusion (I/R) injury." (PMID 37763063, 2023). "Recently, several studies have manifested that the NLRP3 inflammasome serves as a potential therapeutic target for atherosclerosis by regulating the expression of pro-inflammatory factors." (PMID 37370025, 2023).
atherosclerosis (continued). "The inflammatory factors such as IL-1β which are activated by the NLRP3 inflammasome in atherosclerosis activate polymorphonuclear neutrophils, inducing “respiratory burst” and producing a large amount of ROS." (PMID 37155118, 2023). "Recent evidence has suggested that IL-1β-mediated inflammation drives atherothrombotic events, indicating that NLRP3 inflammasome is a major contributor to atherosclerosis." (PMID 37109221, 2023). "The NLRP3 inflammasome is a crucial mediator of various inflammatory diseases, including atherosclerosis and other vascular diseases." (PMID 38004268, 2023). "Many lipoprotein-related components and byproducts mostly studied in macrophages using oxidized or modified LDL in the context of atherosclerosis have been described to regulate the NLRP3 inflammasome." (PMID 37914804, 2023). "In the context of atherosclerosis and coronary artery disease, the expression level of NLRP3 in peripheral blood mononuclear cells (PBMCs) and arterial vascular tissue was positively correlated with the severity of the disease." (PMID 37498354, 2023). "CCs, the major drivers of atherosclerosis, are now considered the most important trigger for NLRP3 inflammasome activation." (PMID 37686238, 2023). "LncRNA MEG3 acts as an endogenous sponge of miR-223 to increase the expression of NLRP3 and its related genes, thereby enhancing endothelial cell pyroptosis and atherosclerosis." (PMID 37498354, 2023). "It has been shown that NLRP3, a predominant component of inflammasome, is involved in the development of atherosclerosis." (PMID 37620556, 2023). "The role of NLRP3 inflammasome activation in atherosclerosis and atherogenesis can be understood by the role of two terrible cytokines produced by it, i.e., IL-1β and IL-18." (PMID 36851139, 2023). "This evidence highlights the contribution of the NLRP3-mediated inflammatory cascade in the development and progression of atherosclerosis in patients with established ASCVD, thus increasing their residual risk of recurrent ischemic events." (PMID 36983163, 2023). "In summary, most clinical and preclinical studies provide evidence for the important role of NLRP3 inflammasome in atherosclerosis." (PMID 37336361, 2023). "A plethora of evidence noted the role of NLRP3 inflammasome in endothelial dysfunction and atherosclerosis." (PMID 37175869, 2023). "Here, a non-genetic model was applied to characterize the role of IL-1α, IL-1β, and NLRP3 for the pathogenesis of atherosclerosis." (PMID 37701434, 2023). "In particular, miR-146a and miR-155 are two of the most studied miRNAs in the field of diabetes and atherosclerosis which control NLRP3 inflammasome activity in macrophages." (PMID 37226245, 2023). "Multiple studies have demonstrated that inhibition of NLRP3 activation has a protective effect on atherosclerosis." (PMID 37155118, 2023). "Experimental evidence has shown that NLRP3 inflammasome activation is the major driver of atherosclerosis." (PMID 36768748, 2023). "Targeting HDAC6 attenuates nicotine-induced macrophage pyroptosis via NF-κB/NLRP3 pathway in atherosclerosis." (PMID 38031118, 2023). "For atherosclerosis, the formation of foam cells was initiated by the release of IL-1β and NLRP3 inflammasomes, which were activated by cholesterol and saturated fatty acids." (PMID 37113481, 2023). "Tranilast blunts NLRP3 inflammasome assembly via enhancing NLRP3 ubiquitination, contributing to the amelioration of vascular inflammation and atherosclerosis." (PMID 37047097, 2023). "Cholesterol-crystal-induced NLRP3 inflammasome activation plays a pivotal role in the pathogenesis of atherosclerosis." (PMID 37765019, 2023).
atherosclerosis (continued). "Recent studies have shown that targeted inhibition of NLRP3 can dampens inflammatory leucocyte production and uptake in atherosclerosis, significantly enhancing reendothelialization and prevent neointimal formation." (PMID 38274313, 2023). "In summary, NLRP3 and IL-1β play an important role in the development and progression of atherosclerosis and in this context are primarily activated by cholesterol crystals and extracellular ATP." (PMID 37239938, 2023). "NLRP3 contributes to the inflammatory process in atherosclerosis, as documented by its activation in arterial walls, on account of lipoprotein accumulation." (PMID 37242177, 2023). "In particular, the nucleotide-binding oligomerization domain and leucine-rich repeat-containing receptor (NLR) family pyrin domain-containing 3 (NLRP3) inflammasome have emerged to be big players in the development of atherosclerosis." (PMID 36983163, 2023). "Upregulation of ASC, caspase-1, and IL-18 was seen in coronary tree segments with advanced atherosclerosis, as well as the presence of NLRP3 inflammasome-positive foam cells around the necrotic core." (PMID 37765019, 2023). "Aside from monocytes and macrophages, accumulating data highlight the role of the NLRP3 inflammasome in other atherosclerosis-relevant cell types." (PMID 37830572, 2023). "NLRP3 activation in macrophages is a critical mechanism driving atherosclerotic inflammation, which ultimately leads to the development of atherosclerosis." (PMID 37374202, 2023). "The aim of this study was to investigate the role of Oridonin, an NLRP3 inflammasome inhibitor, in the progression of atherosclerosis." (PMID 37900059, 2023). "In this study, we investigated the role of NLRP3 in anti-atherosclerosis and anti-NAFLD effect of APN in mouse models with NLRP3 deficiency." (PMID 37198205, 2023). "Taken together, our data demonstrated that APN protects from NAFLD and atherosclerosis through the inhibition of NLRP3 inflammasome." (PMID 37198205, 2023). "A pivotal inflammatory pathway in atherosclerosis downstream of TLR signaling is the nucleotide-binding oligomerization domain-like receptor family pyrin domain-containing 3 (NLRP3) inflammasome pathway." (PMID 37830572, 2023). "Further research is needed to explore the potential role of the NLRP3 inflammasome in the development of atherosclerosis, also considering sex differences." (PMID 37109221, 2023). "NLRP3, NF-kappaB, NLRP3 macrophage, activation, expression and oxidative stress appeared most frequently in this study, except for atherosclerosis." (PMID 37123477, 2023). "Further, its overexpression inhibits pro-inflammatory pyroptosis-related biomarkers known to drive atherosclerosis, such as NLRP3, CASP-1, IL-1β, IL-18, Gasdermin D." (PMID 37226245, 2023). "In a clinical trial, different exercise regimens were effective in reducing NLRP3 gene expression, verifying the potentially important role of this intervention against atherosclerosis." (PMID 37765019, 2023). "Anti-diabetic drugs have recently emerged as important novel mediators in treating diabetic vascular dysfunction and atherosclerosis by inhibiting NLRP3 inflammasome activation and reducing endothelial damage." (PMID 37175869, 2023). "Studies have demonstrated that the expression levels of NLRP3 inflammasome components are upregulated in atherosclerosis, which are potential links to the severity of the disease." (PMID 37109221, 2023). "NLRP3 inflammasome activation also plays a role in atherosclerosis, frailty and cognitive decline, all settings commonly associated with CKD." (PMID 37447158, 2023).
atherosclerosis (continued). "Among the inflammasomes, NLRP3 and AIM2 stand out as key drivers of atherosclerosis, with NLRP3 being the most extensively studied." (PMID 37830572, 2023). "NLRP3 inflammasome is activated not only by microorganisms but also in cases of chronic inflammatory diseases, such as atherosclerosis and Alzheimer’s disease." (PMID 37242177, 2023). "The nucleotide-binding domain (NOD)-like receptor protein 3 (NLRP3) inflammatory corpuscle is believed to be the link between lipid metabolism and inflammation in atherosclerosis." (PMID 37103050, 2023). "Accordingly, NLRP3 involvement in atherosclerosis has been extensively investigated for its prominent role in mediating the release of both IL-1β and IL-18, which contribute to exacerbating vascular inflammation." (PMID 37830572, 2023). "The NLRP3 inflammasome is recognized as a significant contributor to the molecular pathology of atherosclerosis, as evidenced by various studies in animal models and atherosclerotic patients." (PMID 37374202, 2023). "In this review, we introduce the basic cellular and molecular mechanisms of NLRP3 inflammasome activation and its role in atherosclerosis." (PMID 37175869, 2023). "Current studies on the effects of SGLT2i on NLRP3 inflammatory vesicles have focused on diabetic nephropathy, atherosclerosis, steatohepatitis, and cardiomyopathy." (PMID 36589841, 2022). "NLRP3 inflammasome participates in many diseases, such as atherosclerosis, kidney disease, diabetes, and neurodegenerative disorders." (PMID 35754465, 2022). "Nicotine promotes atherosclerosis through the induction of NLRP3-dependent macrophage pyroptosis; HDAC6 depletion abolishes nicotine-caused pyroptosis by inhibiting NLRP3 transcription." (PMID 35565726, 2022). "Ox-LDL is a predominant component in atherosclerosis, which can lead to SMCs pyroptosis by activating NLRP3 inflammasome." (PMID 36304814, 2022). "The current findings support a new role for SalB in decreasing NLRP3 inflammasome activation and subsequent pyroptosis, demonstrating SalB's potential as an agent for treating atherosclerosis." (PMID 35340217, 2022). "Collectively, VX765 functions in mitophagy, efferocytosis, vascular inflammation and atherosclerosis were greatly compromised in Nlrp3−/−;AopE−/− mice." (PMID 35641492, 2022). "It has also been reported that NLRP3 inflammasome inhibition prevents Western diet-induced cardiac hypertrophy, fibrosis and atherosclerosis." (PMID 36311752, 2022). "Oxidized LDL (oxLDL), which is known to accumulate in the vessel wall during atherosclerosis and is phagocyted by macrophages, activates NLRP3 by processes related to influx of Ca2+, reactive oxygen species, and mitochondrial dysfunction, among others." (PMID 35204152, 2022). "Oxidation of low lipoprotein (OX-LDL) activates NLRP3 in the plaque necrosis area formed early in atherosclerosis." (PMID 35321239, 2022). "The NLRP3 inflammasome constitutes a major driver of atherosclerosis, yet the mechanism of action is poorly understood." (PMID 35641492, 2022). "The NLRP3 inflammasome has a crucial role in the process of diverse human inflammatory disorders, including atherosclerosis, diabetes, and Alzheimer’s disease." (PMID 35977927, 2022). "The results of the experiments showed that TXL improved atherosclerosis, especially by reducing the expression of members of the vascular NLRP3 pathway and enhancing the stability of plaques." (PMID 35431939, 2022). "Active inflammasome, especially NLRP3 inflammasome, plays a pivotal role in the development of cardiovascular diseases, such as atherosclerosis, myocardial infarction, and heart failure." (PMID 35464402, 2022). "In the context of diabetes, risk factors such as high glucose, oxidative stress, and inflammation can induce endothelial dysfunction, inflammation, and platelet activation and aggregation by regulating NLRP3 inflammasome, thereby promoting atherosclerosis." (PMID 35844498, 2022).
atherosclerosis (continued). "In certain atherosclerosis models NLRP3 blockage reduced plaque size and myocardial injury after ischemia reperfusion." (PMID 35558073, 2022). "FGF21 can also inhibit endothelial cell pyroptosis mediated by NLRP3 inflammasome and reduce aortic pyroptosis mediated by the NLRP3 inflammasome to prevent atherosclerosis." (PMID 36006939, 2022). "In another study, melatonin prevented atherosclerosis in a mice model of obesity by blocking NLRP3 inflammasome activation by means of SIRT-1 dependent deacetylation and inhibition of NF-kB." (PMID 35204152, 2022). "This work provides mechanistic insights into NLRP3 inflammasome assembly and this inflammasome in dictating atherosclerosis." (PMID 35641492, 2022). "NLRP3 inflammatory vesicles are large multiprotein complexes that regulate IL-1β production and are essential in the development of atherosclerosis." (PMID 35237603, 2022). "Inactivated macrophages, such as the NLRP3 inflammasome, have been regarded as regulators in the pathogenesis of multi-inflammatory diseases like atherosclerosis, sepsis, etc.." (PMID 36232563, 2022). "The activation of the NLRP3 inflammasome in atherosclerosis is primarily driven by oxidized LDL and cholesterol crystals." (PMID 36671400, 2022). "It is noteworthy, however, that although there is increasing interest in the effect of intestinal flora and metabolic pathways on NLRP3 inflammasome activation, research regarding their relation to atherosclerosis is still in its infancy." (PMID 36082127, 2022). "Another study revealed that IL-36Ra protects from atherosclerosis by inhibiting NLRP3 activation, and IL-1β and caspase-1 p10 production." (PMID 35903102, 2022). "Fibroblast growth factor 21 (FGF21), a known risk factor for atherosclerosis, is readily regulated by exercise, and it can inhibit NOD-like receptor protein 3 (NLRP3)-mediated pyroptosis." (PMID 36006939, 2022). "Further studies indicate that the NLRP3 inflammasome is not only involved in early atherosclerosis but also in exacerbating vulnerable plaque formation." (PMID 36082127, 2022). "Mechanisms and target molecules of potential drugs acting on NLRP3 inflammasome in therapies of atherosclerosis (AS)." (PMID 35493086, 2022). "Vascular calcification, which is a general feature in patients with atherosclerosis and T2DM, is also associated with NLRP3 inflammasome activation." (PMID 35844498, 2022). "NLRP3 inflammasome activation have been involved in various inflammatory diseases such as type 2 diabetes, atherosclerosis, gout, Alzheimer’s disease, and inflammatory bowel disease (IBD)." (PMID 35440074, 2022). "Pyroptosis in atherosclerotic lesions mainly depends on the NLRP3 inflammasome activation, and the signaling pathways involved provide some potential targets for novel therapeutic interventions in atherosclerosis." (PMID 36304814, 2022). "NLRP3 inflammasome activation leads to production of active IL-1β and IL-18 as well as pyroptosis, all of which play profound roles in atherosclerosis." (PMID 35641492, 2022). "The vital role of pyroptosis in the pathogenesis of atherosclerosis has generated a few specific inhibitors or agents that target bioactive substances such as NLRP3, caspase-1, caspase-4/5/11, GSDMD, and other candidates in relation to pyroptosis pathway." (PMID 36304814, 2022). "On the other hand, IL-36Ra inhibited the development of atherosclerosis by acting on the NLRP3 inflammasome." (PMID 36613465, 2022). "There are important evidences regarding the involvement of NLRP3 inflammasome in different inflammatory diseases such as cerebral ischemia, Parkinson's and Alzheimer's diseases, inflammatory bowel disease and atherosclerosis." (PMID 36386928, 2022). "On the other hand, pyroptosis by NLRP3 inflammasome causes macrophage and SMC migration and induces foam-cell formation in the advanced stage of atherosclerosis, leading to necrotic core formation." (PMID 35563294, 2022).